CD34 (CD34 molecule)
Diseases named in the same sentence as CD34 in open-access papers (continued):
Sharing a sentence is not in itself a finding about the gene and the disease.
Hypertension (continued). "However, among older men aged 60–69 years, hypertension reduces the number of CD34-positive cells via consumption during activated endothelial repair." (PMID 35365727, 2022). "Since CD34-positive cells contribute to the maintenance of the microcirculation and have a beneficial effect on oxygen supply, the beneficial influence of hypertension on maintaining muscle strength should be limited to participants with a sufficient number of circulating CD34-positive cells." (PMID 36528703, 2022). "CD34-positive cells might contribute to the prevention of hypertension possibly via maintenance of the microcirculation." (PMID 36528703, 2022). "In addition, we also evaluated the effect of circulating CD34-positive cell count (low or high) on the association between γ-GTP and hypertension." (PMID 36528703, 2022). "In conclusion, our study revealed that, in addition to well-established cardiovascular risk factors, handgrip strength is positively associated with hypertension in older men with high CD34-positive cells but not with low CD34-positive cells." (PMID 34088260, 2021). "The effects of Fn1 and Cd34 on hypertension warrant further study." (PMID 34862465, 2021). "The major finding of the present study in older men is that handgrip strength is positively associated with hypertension in participants with high CD34-positive cells, but not in participants with low CD34-positive cells." (PMID 34088260, 2021). "Simple correlation analysis findings show that handgrip strength is significantly positively associated with circulating CD34-positive cell levels but not with serum sodium concentration for subjects with hypertension." (PMID 33441779, 2021). "We also identified 21 DEGs (e.g., Fn1, Cd34, Plpp3, Tns1, Nox4, and Npnt) that may be involved in the development of hypertension." (PMID 34862465, 2021). "This study also showed significant positive association between active arterial wall thickening and CD34-positive cells among subjects without hypertension." (PMID 33549053, 2021). "Although serum sodium concentration is inversely associated with circulating CD34-positive cell levels among subjects without hypertension, no data were available for the evaluation of endothelial function." (PMID 33441779, 2021). "A positive association between handgrip strength and hypertension was found in participants with high circulating CD34-positive cell level, but not in those with low circulating CD34-positive cell level." (PMID 34088260, 2021). "The circulating CD34+ cell count was significantly positively associated with active arterial wall thickening among subjects without hypertension (n = 236), but not among subjects with hypertension (n = 127)." (PMID 32170211, 2020). "In conclusion, for elderly subjects without hypertension, the CD34+ cell count is significantly positively associated with active arterial wall thickening, but not for elderly subject with hypertension." (PMID 32170211, 2020). "The simple correlation coefficient showed a significant positive association between circulating CD34+ cells and platelets only for subjects without hypertension." (PMID 32170211, 2020). "Circulating CD34+ cells are positively associated with active arterial wall thickening in subjects without hypertension." (PMID 32170211, 2020). "The major findings of the present study were that, in elderly men without hypertension, the CD34+ cell count was significantly positively associated with active arterial wall thickening, but not for subjects with hypertension." (PMID 32170211, 2020). "According to univariate linear regression analysis, hypertension, heart failure, decreased eGFR, circulating EPCs (both CD34+KDR+ and CD34+KDR+CD133+ cells), and increased inflammatory biomarkers (hsCRP, IL-1β, and TMAO) were all significantly associated with lower FMD." (PMID 30862856, 2019).
Hypertension (continued). "Our previous study found that platelet count is positively associated with hypertension in participants with low, but not high, circulating CD34-positive cell levels." (PMID 29724162, 2018). "Independent of known cardiovascular risk factors, HDL was found to be positively associated with hypertension in subjects with a high level of circulating CD34-positive cells but not for subjects with low circulating CD34-positive cells." (PMID 28619079, 2017). "Since HDL mediates important protective actions on the vascular endothelium by increasing the number of circulating endothelial progenitor cells (CD34-positive cells), the level of circulating CD34-positive cells should influence the association between HDL and hypertension." (PMID 28619079, 2017). "In conclusion, we found that HDL is significantly positively associated with hypertension among subjects with a high level of CD34-positive cells but not among subjects with low CD34-positive cells." (PMID 28619079, 2017). "Therefore, in our present study, although the statistical power was not significant, an inverse tendency was observed between HDL and hypertension for subjects with a low level of CD34-positive cells." (PMID 28619079, 2017). "The precise mechanism of action governing the association between HDL concentration in the blood and CD34-positive cells on hypertension risk is not understood." (PMID 28619079, 2017). "In conclusion, our findings demonstrate that platelet count indicates vascular repair activity, and that hypertension might mask the beneficial effects of circulating CD34-positive cells." (PMID 27374094, 2016). "Since CD34-positive cells also contribute to the maintenance of the microcirculation by promoting angiogenesis and neovascularization, individuals with aggressive endothelial repair also have lower peripheral blood pressure resistance, which has the beneficial effect of preventing hypertension." (PMID 37511963, 2023). "Therefore, among participants with low circulating CD34-positive cell counts, platelet count could indicate insufficient endothelial repair related to hypertension." (PMID 37511963, 2023). "Furthermore, circulating CD34-positive cell count was significantly positively associated with active arterial wall thickening only in men without hypertension." (PMID 36528703, 2022). "Therefore, hypertension could disappear among older participants with a sufficient number of circulating CD34-positive cells." (PMID 36528703, 2022). "This means that platelets could be positively associated with circulating CD34-positive cell levels, as observed in our subjects without hypertension." (PMID 33441779, 2021). "Therefore, participants with high CD34-positive cells might possess a higher activity for microcirculation maintenance, which results in a lower prevalence of hypertension." (PMID 34088260, 2021). "However, in the present study, a significant positive association between handgrip strength and hypertension was observed in participants with high CD34-positive cells but not in participants with low CD34-positive cells." (PMID 34088260, 2021). "However, in the present study, the positive association between circulating CD34+ cells and active arterial wall thickening is observed only in subjects without hypertension." (PMID 32170211, 2020). "However, the ratio of the decrease in the platelet count due to their use in endothelial repair might be much smaller than that of circulating CD34+ cells in patients with hypertension." (PMID 32170211, 2020). "For our study participants with higher levels of circulating CD34-positive cells, a significant positive association was observed between platelets and circulating CD34-positive cells among those without hypertension, and a significant inverse association among those with hypertension." (PMID 30695751, 2019).
Hypertension (continued). "The major findings of the present study are that, independent of known cardiovascular risk factors, HDL is significantly positively associated with hypertension among subjects with a high level of CD34-positive cells but not for subjects with low CD34-positive cells." (PMID 28619079, 2017). "Therefore, the presence of hypertension might act as a confounding factor in the correlation between platelet count and the number of circulating CD34-positive cells." (PMID 27374094, 2016). "In the present study, we provided evidence that CD34+ cells can differentiate into a special type of fibroblast called FABP4+ fibroblasts in the presence of hyperlipidemia and hypertension." (PMID 39198543, 2024). "However, it is still unclear whether CD34+ cells exhibit altered differentiation potential in the metabolic microenvironment (especially in lipid metabolism disorders) under conditions of hypertension and hyperlipidemia and whether CD34+ cells play a role in cardiac fibrosis." (PMID 39198543, 2024). "Therefore, we hypothesized that the level of circulating CD34+ cells is positively associated with active arterial wall thickening in the elderly, but only in those without hypertension." (PMID 32170211, 2020). "Circulating CD34-positive cells have also been revealed to play an important role in vascular endothelial repair in conjunction with platelets, and platelets are significantly positively associated with hypertension in participants with low, but not high, circulating CD34-positive cell levels." (PMID 29724162, 2018). "Patients with a higher number (above 25th percentile) of CD34+/KDR+ and CD34+/VE-cadherin+ and lower of CD14+/endoglin+ cells (equal or below 75th percentile) were younger, with less years since diagnosis of hypertension, and with lower BP." (PMID 29304136, 2018). "Additionally, hypertension might mask the beneficial effects of circulating CD34-positive cells." (PMID 27374094, 2016). "In order to evaluate the relation of impaired global strains with CD34+ EPCs and SOD, multivariate adjustment for age, gender, BMI, smoking history, hypertension, hypercholesterolaemia and HbA1c was performed." (PMID 23217199, 2012). "Participants with hypertension had 4-fold increase in CD34 + KDR + EPC subtype numbers compared to those without." (PMID 39186241, 2024). "In a cross-sectional study, among those with enough circulating CD34-positive cells, γ-GTP levels were revealed to be positively associated with structural atherosclerosis but not with hypertension." (PMID 37511963, 2023). "In this study, we found a significant positive association between active arterial wall thickening and circulating CD34-positive cell count only among participants without hypertension." (PMID 36528703, 2022). "Among men with hypertension, platelet count was revealed to be significantly positively associated with CIMT, but not with circulating CD34-positive cell count." (PMID 36528703, 2022). "The cardiovascular risk factor-adjusted ORs of active arterial wall thickening for the logarithmic circulating CD34+ cell count were 0.69 (0.36, 1.32) for subjects with hypertension and 1.83 (1.19, 2.84) for subjects without hypertension." (PMID 33549053, 2021). "Simple correlation analysis findings demonstrate that for subjects without hypertension, circulating CD34-positive cell levels are significantly positively correlated with platelet concentration but inversely correlated with serum sodium concentration." (PMID 33441779, 2021). "In our current study, we identified a significant inverse correlation between serum sodium concentration and circulating CD34-positive cell levels in subjects without hypertension." (PMID 33441779, 2021). "Results of simple correlation analysis show that handgrip strength is significantly positively associated with serum sodium concentration but not with circulating CD34-positive cell levels for subjects without hypertension." (PMID 33441779, 2021).
Hypertension (continued). "The fully adjusted odds ratios (ORs) of active arterial wall thickening for the logarithmic circulating CD34+ cell count were 1.83 (1.19, 2.84) and 0.69 (0.36, 1.32) for subjects without and with hypertension, respectively." (PMID 32170211, 2020). "Throughout the 8-weeks time course of hypertension, the amount of CD34 staining did not change significantly in the P-Ao or the LAD relative to control." (PMID 23162468, 2012). "For individuals with high CD34-positive cell counts (≤median), γ-GTP was significantly and positively associated with structural atherosclerosis (OR for the log-transformed value of γ-GTP = 2.26 (1.32, 3.86)) but not with hypertension (OR = 0.77 (0.51, 1.17))." (PMID 37511963, 2023). "Participants with controlled hypertension might have higher activity of CD34-positive cells than those who do not have hypertension but have a lower rate of CD34-positive cell reduction than those with uncontrolled hypertension." (PMID 34088260, 2021). "Therefore, subjects with hypertension should have stronger wasting reduction in circulating CD34+ cells than those without hypertension." (PMID 32170211, 2020). "Previously, we reported that among subjects with hypertension, platelet count is positively associated with CIMT but not with circulating CD34-positive cells, since consumptive reduction of circulating CD34-positive cells is induced by aggressive vascular repair." (PMID 29050209, 2017). "Additionally, among subjects with a low level of CD34-positive cells, a tendency toward an association between HDL and hypertension was observed, although this was not significant." (PMID 28619079, 2017). "Interestingly, the endothelial cells in the LAD and MCA were not all positive for CD34 at 2 weeks of hypertension, though they again stained positive for CD34 at 4 weeks of hypertension." (PMID 23162468, 2012). "A previous study has shown CD34 + and CD34 + KDR + cell numbers to be reduced in poorly controlled hypertensive patients, unfortunately, it is not possible to ascertain whether the participants in our study had poorly controlled hypertension and therefore this would need further investigation." (PMID 39186241, 2024). "Reduction of circulating CD34-positive cells due to consumption might therefore determine the number of circulating CD34-positive cells in subjects with hypertension but not in those without hypertension." (PMID 33441779, 2021). "In individuals without hypertension, platelet count was not significantly correlated with CIMT (β = −0.05, p = 0.356), but platelet count was significantly positively correlated with the natural log of circulating CD34-positive cell count (β = 0.26, p < 0.001)." (PMID 37511963, 2023). "Independent of known cardiovascular risk factors, platelet count was found to be significantly positively correlated with circulating CD34-positive cell count (standardized parameter estimate (β) = 0.26, p < 0.001) but not with CIMT (β = − 0.05, p = 0.356) in men without hypertension." (PMID 36528703, 2022).
sarcoma (38 papers, 1997 to 2025). A usually aggressive malignant neoplasm of the soft tissue or bone. "The presence of the CD34 marker was associated with a milder/better evolution of the sarcomas in the studied group." (PMID 40362599, 2025). "The second bone marrow biopsy, which was performed due to the partial response to sarcoma treatment, showed hypercellular bone marrow with CD34 and CD61-positive spindle cell infiltration and > 20% basophilic blasts with cytoplasmic blebs." (PMID 38374236, 2025). "In our study, we aimed to detect PRDM10 gene rearrangement in superficial CD34-positive fibroblastic tumors and other pleomorphic sarcomas included in its differential diagnosis by immunohistochemistry and Fluorescence in situ hybridization." (PMID 40560238, 2025). "In a sarcoma study, median CD34 based IMVD was 44.6 for Ewing’s sarcoma, 39.7 for osteosarcomas, and 12.9 for chondrosarcomas." (PMID 37296922, 2023). "At the same time, CD34—an endothelial cell marker—is also considered as one of the main activators of angiogenesis in sarcomas, including sarcoma recurrence." (PMID 37296922, 2023). "It is possible that MFSs and UPSs initially develop as relatively well-differentiated fibroblastic/myofibroblastic sarcomas originating from CD34 + SFCs, but lose their CD34 expression while simultaneously gaining highly malignant features." (PMID 34326362, 2021). "The LMNA-NTRK1 fusion-positive sarcoma revealed CD34/S100 protein/nestin/CD10 coexpression, and a low mitotic rate." (PMID 32957984, 2020). "S100-protein and CD34 co-positivity are generally rare in sarcomas; these can be interpreted as hybridomas or evidence of dual differentiation." (PMID 32957984, 2020). "Even after the detection of the mesenteric primary, the patient was initially treated as a mesenteric sarcoma as histopathology showed a sarcoma which was positive for CD34 and vimentin antigen." (PMID 17105654, 2006). "This means that complete inhibition of P-gp function in these sarcoma cells would lead to an increase of daunorubicin accumulation with 170% compared with 30% in the CD34+ cells." (PMID 9376262, 1997). "FS-DFSP with atypical staining for CD34 could be confused with high-grade sarcomas, such as high-grade infantile fibrosarcoma (IFS) with ETV6-NTRK3 fusion, especially dedifferentiated liposarcoma (DDL) without a well-differentiated liposarcoma (WDL) component." (PMID 36776313, 2023). "Also, the TPR-NTRK1 fusion-positive sarcoma showed robust positivity for CD34/nestin, and also showed high mitotic rate." (PMID 32957984, 2020). "Both are having negative expression of basal keratin and beta catenin, so the expression of Ki67 index together with stromal positivity of CD34 may aid in the diagnosis of PT over the sarcoma." (PMID 32986365, 2020). "In the case of LMNA-NTRK1 fusion sarcoma, S100/CD34/CD10-coexpression was a novel finding." (PMID 32957984, 2020). "Extensive investigations have confirmed that tumor growth and metastasis depend on angiogenesis, and multiple angiogenic factors such as vascular endothelial growth factor (VEGF), bFGF, TGF-β1, MMP, cyclooxygenase-2 (COX-2), CD34, and c-KIT are associated with the prognosis of sarcoma." (PMID 28969086, 2017). "Individual sarcomas were found to have high P-gp function compared with CD34+ cells." (PMID 9376262, 1997). "In conclusion, we suggested that PRDM10 gene rearrangement is not limited to superficial CD34-positive fibroblastic tumors; undifferentiated pleomorphic sarcomas may exhibit this molecular alteration and immunohistochemistry has lower sensitivity than fluorescence in situ hybridization." (PMID 40560238, 2025). "It showed an undifferentiated pleomorphic sarcoma of the aortic intima with positive staining for vimentin and smooth muscle actin but inconclusive for genetic markers such as CD31, CD34, and other frequent markers." (PMID 40034398, 2025).